CCL4 (C-C motif chemokine ligand 4)
Description:
Monokine with inflammatory and chemokinetic properties. Binds to CCR5. One of the major HIV-suppressive factors produced by CD8+ T-cells. Recombinant MIP-1-beta induces a dose-dependent inhibition of different strains of HIV-1, HIV-2, and simian immunodeficiency virus (SIV). The processed form MIP-1-beta(3-69) retains the abilities to induce down-modulation of surface expression of the chemokine receptor CCR5 and to inhibit the CCR5-mediated entry of HIV-1 in T-cells. MIP-1-beta(3-69) is also a ligand for CCR1 and CCR2 isoform B.
Synonyms: LAG-1; MIP-1-beta; ACT-2; LAG1; MIP1B; SCYA4; AT744.1; ACT2; G-26; HC21; MIP1B1; SCYA2
Tractability: Antibody: its Gene Ontology location is reachable by antibodies, with high confidence; UniProt places it where antibodies can reach, with medium confidence; UniProt predicts a signal peptide or a membrane-spanning region.
Gene: Protein-coding gene on chromosome 17 (36,103,827 to 36,105,621, forward strand). Ensembl gene ENSG00000275302.
Subcellular location: Secreted
Pathways (Reactome):
Signal Transduction: Chemokine receptors bind chemokines; G alpha (i) signalling events
Immune System: Interleukin-10 signaling
Gene Ontology:
Molecular function: CCR1 chemokine receptor binding; CCR5 chemokine receptor binding; identical protein binding; protein binding; CCR chemokine receptor binding; chemokine activity; cytokine activity
Biological process: host-mediated suppression of viral transcription; positive regulation of calcium ion transport; positive regulation of calcium-mediated signaling; positive regulation of natural killer cell chemotaxis; response to toxic substance; antimicrobial humoral immune response mediated by antimicrobial peptide; cell adhesion; cell-cell signaling; chemokine-mediated signaling pathway; eosinophil chemotaxis; establishment or maintenance of cell polarity; immune response; inflammatory response; positive regulation of cell migration; response to virus; signal transduction
Cellular component: extracellular region
Genetic constraint (gnomAD): Loss-of-function variants: 8 observed, 9.95 expected, observed/expected ratio (o/e) 0.8, 90% interval 0.47 to 1.44. That is too few expected variants to judge how well the gene tolerates losing a copy. Missense variants: 106 observed, 113.88 expected, observed/expected ratio (o/e) 0.93, 90% interval 0.79 to 1.09. Synonymous variants: 35 observed, 43.44 expected, observed/expected ratio (o/e) 0.81, 90% interval 0.61 to 1.07.
Homologues: Orthologues: chimpanzee CCL4 (97% identical), macaque CCL4L1 (91% identical), mouse Ccl4 (76% identical), rat Ccl4 (76% identical), zebrafish ccl35.1 (36% identical), zebrafish ccl35.2 (36% identical). Paralogues in human: CCL4L2 (91% identical), CCL3L3 (59% identical), CCL3 (58% identical), CCL5 (46% identical), CCL14 (43% identical), CCL23 (42% identical), CCL11 (41% identical), CCL15 (41% identical), CCL18 (41% identical), CCL21 (41% identical), CCL16 (40% identical), CCL13 (39% identical), and 14 more.
Diseases named in the same sentence as CCL4 in open-access papers:
CCL4 is named in the same sentence as 424 diseases in open-access papers, as found by Europe PMC text mining. Sharing a sentence is not in itself a finding about the gene and the disease. The quoted sentences say what the papers report.
liver fibrosis (252 papers, 1996 to 2025). "Wild-type (WT) and conditional UBC-Cre; Men1f/f (Men1Δ/Δ) allele homozygous knockout (KO) mice were treated with CCL4 to establish liver fibrosis models." (PMID 40651612, 2025). "The CCL4 model provides a valuable tool for researchers to investigate the underlying mechanisms of liver fibrosis and to test novel therapeutic strategies aimed at reversing or halting the progression of this disease." (PMID 39388703, 2025). "The schistosome parasite contains more than 10,000 putative encoding genes, making the mechanism of schistosome-induced liver fibrosis more complex and distinct from other fibrosis models, such as the CCL4 chemically induced hepatic fibrosis model." (PMID 39363237, 2024). "Hepatoprotective effects (alleviated liver fibrosis caused by CCL4 by promoting GPxs synthesis and increasing MMP9 mRNA expression)." (PMID 38202719, 2023). "The SeP extracted from soybean alleviated liver fibrosis caused by chemokine ligands 4 (CCL4) by promoting GPxs synthesis and increasing the mRNA expression of matrix metallopeptidase 9 (MMP9) in rats." (PMID 38202719, 2023). "Ethanol along with CCL4 treatment was subjected to hepatocyte-specific HIF-1α-deficient in their study, which resulted in increased liver fibrosis induced by CCL4." (PMID 36523459, 2022). "Even though C57BL/6 mice are less susceptible than Balb/c mice to CCL4-induced liver fibrosis, various gene knockout mice in the C57BL/6 background have immensely contributed to the molecular understanding of liver fibrosis pathogenesis." (PMID 34712238, 2021). "Together these data demonstrate that CDH11-/- deficient mice have markedly attenuated liver fibrosis compared to WT mice in the CCL4 mice model." (PMID 31269038, 2019). "Blockage or deficience of CXCL10 leads to the reduced liver fibrosis in CCL4 induced liver fibrosis model." (PMID 22905138, 2012). "We observed a characteristic miRNA expression profile common to both human liver biopsy specimens and mouse CCL4 specimens, comprising the key miRNAs which are associated with the liver fibrosis." (PMID 21283674, 2011). "We revealed that Men1 loss promoted CCL4- or high-fat diet-induced liver fibrosis." (PMID 40651612, 2025). "However, oral administration of PAs into CCl4-induced liver fibrosis caused a significant (P < 0.05) improvement in the levels of these antioxidants in the liver compared with the CCL4-treated rats." (PMID 35881285, 2022). "We found that the induction of liver fibrosis by CCL4 was associated with TIM‐4 expression in KCs." (PMID 31755616, 2020). "Furthermore, compared to WT mice, CDH11 deficient mice develop significantly less liver fibrosis when administered CCL4." (PMID 31269038, 2019). "Liver fibrosis more severe in Mif-deficient mice (both CCL4- and TAA-induced)." (PMID 26124760, 2015). "In addition, CCL4 caused a dose-dependent progression of liver fibrosis." (PMID 32046285, 2020). "In this study, a CCL4-induced liver fibrosis model was employed to assess the therapeutic potential of MSCs-sEVs." (PMID 40873954, 2025). "For analyzing how miRNA-125a-5p affected mouse liver fibrosis, this study constructed the CCL4-mediated mouse liver fibrosis model." (PMID 40890107, 2025). "We have shown that treatment with exosomes derived from intestinal organoids substantially ameliorated liver fibrosis in CCL4‐induced mouse models." (PMID 40619613, 2025). "To examine the effect of Huangqi Decoction on liver fibrosis, we constructed a hepatic fibrosis rat model induced by CCL4." (PMID 39388703, 2025). "After 2 or 5 weeks of treatment with EXOs, mice with CCL4‐induced liver fibrosis (CCL4+ EXOs) exhibited liver weight/body weight ratios similar to those in the control groups (Oil+ PBS)." (PMID 40619613, 2025). "JIB-04, an H3K36me3 agonist, effectively suppressed KC activation induced by Men1 or Setd2 deletion by reactivating IL-10 expression and further alleviated CCL4-induced liver fibrosis symptoms." (PMID 40651612, 2025).
liver fibrosis (continued). "In vivo, in a CCL4-induced liver fibrosis mouse model, miR-99a-5p reduced M2 marker expression and simultaneously reduced the production of collagen type I and III." (PMID 40211350, 2025). "To identify the signaling pathways involved in DMDD alleviation of liver fibrosis, we performed transcriptome sequencing of the CCL4 model group and DMDD-treated mouse liver." (PMID 40453659, 2025). "Men1 expression was significantly decreased in mouse liver fibrosis models induced by Methionine-Choline Deficient Diet (MCD), CCL4, and Bile Duct Ligation (BDL)." (PMID 40651612, 2025). "The Hematoxylin–eosin (HE) staining, MASSON trichrome staining, and α‐SMA staining results displayed that treatment with EXOs led to a significant reduction of the liver fibrotic area in mice with 6‐week and 9‐week CCL4‐induced liver fibrosis." (PMID 40619613, 2025). "Liver sections of the CCL4/mice that received Silymarin (positive control) detected mild to moderate periportal hepatic fibrosis." (PMID 39910080, 2025). "DHM enhances IFN-γ expression through the NF-κB/STAT3 pathway to improve NK cell killing, inhibits HSCs activation and significantly improves the CCL4-induced liver fibrosis." (PMID 40761743, 2025). "We established hepatocyte-specific Men1-KO mice (albumin-cre; Men1f/f, Men1ΔH/ΔH), and a liver fibrosis model was established by treating mice with CCL4." (PMID 40651612, 2025). "Sirius Red staining in the DEN/CCL4‐induced model further revealed that NAT10‐2023 significantly alleviated liver fibrosis progression." (PMID 41476650, 2025). "In our study, we found that both MSCs and MSCs-sEVs exhibited therapeutic effects on CCL4-induced liver fibrosis in mice." (PMID 40873954, 2025). "Results from HE, Sirius red staining and WB demonstrated that the degree of liver fibrosis increased with prolonged CCL4 treatment." (PMID 40406118, 2025). "A study reported that using IL-10-modified bone marrow-derived DCs, where the DCs were immature and infused into CCL4-induced hepatic fibrotic mice, significantly alleviated liver fibrosis." (PMID 39995661, 2025). "Using a CCL4-induced liver fibrosis model, Setd2ΔM/ΔM led to an increase in SR, α-SMA, and F4/80 staining." (PMID 40651612, 2025). "The EXOs isolated from human Int‐Orgs were administered to mice with liver fibrosis induced by CCL4." (PMID 40619613, 2025). "The present study aims to investigate the effects and molecular mechanisms of Huangqi Decoction on autophagy and apoptosis in liver tissues induced by CCL4-induced liver fibrosis." (PMID 39388703, 2025). "It was found that the DMDD treatment group reduced the weight of the liver with CCL4-induced liver fibrosis." (PMID 40453659, 2025). "For instance, in a CCL4-induced liver fibrosis model, FGF15 knockout mice exhibited reduced liver fibrosis, suggesting that FGF15 plays a role in fibrotic progression." (PMID 39781450, 2025). "Sirius Red staining in the DEN/CCL4‐induced model showed that NAT10 knockdown effectively suppressed liver fibrosis progression." (PMID 41476650, 2025). "Altogether, the combined data approved the potential of VA + BTZ synthesized NPs in surpassing the interaction between TGF-β1 and NF-κB signaling pathways and further attenuating hepatic fibrosis in a CCL4-induced mouse model of hepatic fibrosis." (PMID 40636301, 2025). "Liver sections of CCL4/mice post-treated with J. rubens extract showed hepatic fibrosis limited to the periportal area (collagen deposition) and portal inflammation (mononuclear inflammatory cells infiltration), smudge-shaped pyknosis nucleus." (PMID 39910080, 2025). "Using a CCL4-induced liver fibrosis model, we found that we found that α-SMA and SR staining was enhanced and the number of F4/80+ MACs was also increased in the Men1ΔM/ΔM group." (PMID 40651612, 2025). "In the current investigation, we mainly assessed the impacts of both BTZ in VA-coupled NPs and systematic BTZ administration on CCL4-induced hepatic fibrosis mice." (PMID 40636301, 2025).
liver fibrosis (continued). "In this study, we explored the effect of Huangqi Decoction on autophagy and apoptosis in liver tissue of CCL4-induced hepatic fibrosis rats." (PMID 39388703, 2025). "Treatment with exosomes derived from intestinal organoids ameliorated liver fibrosis in a mouse model of CCL4‐induced liver fibrosis." (PMID 40619613, 2025). "And in a murine model of hepatic fibrosis induced by CCL4, increased EGFR expression and STAT3 activation in hepatic macrophages were positively associated with M1 macrophage infiltration and collagen deposition." (PMID 41181146, 2025). "Tan and his team induced liver fibrosis in mice by injecting CCL4 and found that Fas/FasL-regulated hepatocyte apoptosis is involved in the process of liver fibrosis." (PMID 40406118, 2025). "Surprisingly, Gab1 mRNA and relative protein levels are significantly increased in CCL4-induced liver fibrosis mice compared to those in control mice." (PMID 38935609, 2024). "A recent study in CCL4-induced liver fibrosis in rats has found that the suppression of the Hh pathway by empaflifozin resulted in a reduction in the severity of fibrosis, possibly mediated through the inhibition of ER stress." (PMID 39201329, 2024). "report that the adoptive transfer of anti-inflammatory macrophages can alleviate CCL4-induced liver fibrosis in mice." (PMID 39635524, 2024). "In our research, we examined the effects of UC-MSC-CM, enriched with soluble factors from MSCs, on CCL4-induced liver fibrosis in rats." (PMID 38874773, 2024). "In our current exploration, we primarily focused on assessing the impact of MSC-CM administration in a rat model with CCL4-induced liver fibrosis." (PMID 38874773, 2024). "Neutrophils have anti-inflammatory properties and protective effects in both bile duct ligation and CCL4-induced liver fibrosis." (PMID 38481992, 2024). "The results showed that treatment with phyllanthin nanoparticles resulted in decreased ALT and AST levels, repair of cell membrane damage from CCL4, and improvement in liver fibrosis." (PMID 39185304, 2024). "In vivo, miR-26a mimic-Exo decreased the level of SLC7A11 and attenuated CCL4-induced liver fibrosis." (PMID 38756248, 2024). "The inhibition of ccl4-induced liver fibrosis by TIM-4 is achieved through interference with KCs via the Akt4/mitophagic signaling pathway, and it also delays the progression of NAFLD." (PMID 39175576, 2024). "A previous study has demonstrated the crucial impact of HDAC4 in regulating ECM deposition in a liver fibrosis model induced by CCL4." (PMID 38221603, 2024). "Our study identified 230 Co-DEGs by analyzing transcriptomic data of primary LSECs from three different liver fibrosis mouse models (CCL4, CDAA, and NASH)." (PMID 39194690, 2024). "In the CCL4-induced liver fibrosis model, oroxylin A significantly upregulated autophagy expression and alleviated liver fibrosis." (PMID 38393131, 2024). "Phyllanthin nanoparticles, prepared with PLGA, acetone, and Tween via the nanoprecipitation method, were administered to a CCL4-induced liver fibrosis model." (PMID 39185304, 2024). "In a rat model of CCL4-induced liver fibrosis, miR-23a induces liver fibrosis through the PTEN/PI3K/Akt/mTOR/snail signaling pathway, while lncRNA-GAS5 acts as a ceRNA to decrease miR-23a expression and suppressing liver fibrosis." (PMID 39044218, 2024). "In a mouse model of CCL4-induced liver fibrosis, treatment with kaempferol led to improved collagen deposition and reduced expression of α-SMA and COL1α1." (PMID 39185304, 2024). "It is widely believed that ghrelin reduces hepatic fibrosis via the traditional Smad-dependent TGF-β pathway, including hepatic fibrosis induced by CCL4 in a rodent model." (PMID 39569809, 2024). "We demonstrate that blocking antibodies against α4β7 and MAdCAM-1 that reduce recruitment of α4β7+ CD8 T cells to the liver improves CCL4-induced hepatic fibrosis." (PMID 38727292, 2024).
liver fibrosis (continued). "CHA also prevents CCL4-induced liver fibrosis by suppressing oxidative stress in the liver and hepatic stellate cells." (PMID 38323084, 2024). "The results showed that 1498 upregulated and 434 downregulated genes were differentially expressed in LSECs during liver fibrosis induced by CCL4 in the GSE120281 dataset." (PMID 39194690, 2024). "ATF3 has been implicated in fibrosis, with studies showing its upregulation in the CCL4‐induced mouse liver fibrosis model." (PMID 39031798, 2024). "Together, these results indicated that BMSC-derived exosomal miR-26a reduced the level of SLC7A11 and relieved CCL4-induced liver fibrosis in mice." (PMID 38756248, 2024). "After treatment with β-sitosterol, CCL4-induced hepatic fibrosis was reversed in mice, while inflammatory and hepatic fibrosis indices were improved." (PMID 38461449, 2024). "To test this, we determined a pathologic role of Gab1 in the progression of liver fibrosis in vivo using the established murine model of liver fibrosis induced by CCL4 treatment." (PMID 38935609, 2024). "Liver function: Cy-3G with CCL4 inhibited liver fibrosis and the activation of hepatic stellate cells." (PMID 38794640, 2024). "Consistent with previous studies, we found that AHR significantly alleviates CCL4‐induced liver fibrosis by inducing ferroptosis in mHSCs." (PMID 39654034, 2024). "Administering fibrosis-free EVs to mice with CCL4-induced liver injury has been shown to suppress hepatocellular damage and liver fibrosis, reducing the number of inflammatory cytokines and transaminases in the blood." (PMID 37833930, 2023). "Moreover, macrophages could transform into myofibroblasts in CCL4-induced liver fibrosis model, high-fat diet (HFD) and methionine-choline-deficient diet (MCD)-induced nonalcoholic fatty liver diseases (NAFLD) model, and ethanol-induced alcoholic fatty liver diseases (AFLD) model." (PMID 37941043, 2023). "For instance, folic acid ameliorated CCL4-induced liver fibrosis by reducing inflammation and RO production." (PMID 37047834, 2023). "Previous studies demonstrated that H19 was highly elevated in the liver of NASH, cholestatic, and CCL4‐induced liver fibrosis." (PMID 37398637, 2023). "Inconclusion, we developed curcumin/collagen/PCL/PLGA nanoscaffold with control release of cur to elicit the MSCs to ameliorate CCL-4 induced liver fibrosis." (PMID 37064607, 2023). "ALKBH5 is down‐regulated in liver tissues of a CCL4‐induced mouse liver fibrosis model and in TGF‐β‐stimulated activated HSC in vitro, whereas high expression of ALKBH5 ameliorates liver fibrosis and inhibits HSC activation." (PMID 36792369, 2023). "Models of hepatic fibrosis such as the CCL4 model, HFD-induced NAFLD model, MCD-induced NAFLD model and ethanol-induced AFLD model were demonstrated and were stained with immunofluorescence." (PMID 37941043, 2023). "For instance, silencing lnc-LFAR1 decreases TGFβ-induced hepatocyte apoptosis, impairs HSC activation in vitro, and alleviates liver fibrosis induced by CCL4." (PMID 36985369, 2023). "In a study by Fathy et al42 adipose tissue-derived MSC (ASC) along with eugenol preconditioned ASC were injected in CCL4 model of liver fibrosis." (PMID 37052348, 2023). "Our previously published results demonstrated a profound effect of 4MU on gene expression after two weeks of treatment and its cessation after four weeks in CCL4 induced murine model of hepatic fibrosis." (PMID 36768453, 2023). "Our previous study demonstrated augmented mitochondrial fission in a CCL4-induced mouse model of liver fibrosis." (PMID 38139341, 2023). "Milosavljevic et al41 investigated the role of MSCs in modulating IL-17 signaling and its subsequent effect on CCL4 induced hepatic fibrosis in mice." (PMID 37052348, 2023).